RNU2-29P (RNA, U2 small nuclear 29, pseudogene)
Gene: Small nuclear RNA gene on chromosome 7 (53,776,136 to 53,776,324, forward strand). Ensembl gene ENSG00000222355.
Homologues: Orthologues: chimpanzee U2 (99% identical), macaque U2 (74% identical). Paralogues in human: U2 (68% identical), RNU2-6P (66% identical), RNU2-14P (66% identical), RNU2-3P (66% identical), U2 (66% identical), RNU2-26P (65% identical), RNU2-2 (64% identical), RNU2-57P (64% identical), RNU2-59P (64% identical), RNU2-64P (64% identical), RNU2-56P (63% identical), RNU2-36P (63% identical), and 65 more.